BAP1 (BRCA1 associated deubiquitinase 1)
Diseases named in the same sentence as BAP1 in open-access papers (continued):
Sharing a sentence is not in itself a finding about the gene and the disease.
lung carcinoma (33 papers, 2012 to 2025). "Current blood-based tumor markers show limited accuracy; for instance, the loss of BAP-1 used to distinguish MM from lung cancer which exhibits highly variable sensitivity (55–85%) despite high specificity (98–100%)." (PMID 41438104, 2025). "Deletions, loss of heterozygosity, missense mutations, and large rearrangements in the BAP1 gene locus have been found in lung and sporadic breast tumors and lung cancer cell lines." (PMID 33529461, 2021). "Consistent with this, lung cancer cells with mutant BAP1 typically possess truncations or other mutations that negatively impact its deubiquitinase and nuclear localization ability." (PMID 29166932, 2017). "BAP1 was first identified as tumor suppressor, when mutations were reported in lung cancer cell lines." (PMID 25970771, 2015). "In contrast to downregulation in MPM, miR-31-5p was shown to be overexpressed in both mouse and human lung cancers, and to exhibit oncogenic activity in lung cancer cell lines and in xenografts, with the latter observation linked to its control of BAP1 expression." (PMID 32117755, 2020). "Previous reports suggested that overexpression of BAP1 in lung cancer cells inhibited tumor growth in mice, and BAP1 has few mutations in lung cancer, suggesting that there may be another pathway involved in the dysregulation of BAP1." (PMID 29159179, 2017). "Accumulating evidence has implicated BAP1 as a tumor suppressor since frequent loss of heterozygosity, large rearrangements, deletions and missense mutations of the BAP1 gene have been found in breast tumors and lung cancer." (PMID 27553041, 2016). "BRCA1-associated protein-1 (BAP1) is an important nuclear-localized deubiquitinating enzyme that serves as a tumor suppressor in lung cancer; however, its function and its regulation are largely unknown." (PMID 26885612, 2016). "In Lung cancer tissues, BAP1 mRNA levels demonstrated an inverse correlation with miR-7974 expression but exhibited a positive correlation with circ_0007552 expression." (PMID 40918144, 2025). "Examples include BAP1 in cervical and lung cancer, CDK1 in bladder cancer, E2F2 in ovarian cancer, and RHOA, VEGF, NUMB, among others, in oral cancer." (PMID 41373532, 2025). "Circ_0007552 inhibits the development, progression, and metastasis of lung cancer by sponging miR-7974 to upregulate BAP1 expression." (PMID 40918144, 2025). "qRT-PCR and Western blot analyses revealed that Circ_0007552 overexpression upregulated BAP1 mRNA and protein levels in lung cancer cells, while si-BAP1 transfection attenuated this regulatory effect." (PMID 40918144, 2025). "Functional assessments including CCK-8, colony formation, and Transwell migration and invasion assays demonstrated that BAP1 knockdown reversed the inhibitory effects of Circ_0007552 overexpression on lung cancer cell proliferation, migration, and invasion." (PMID 40918144, 2025). "Similar pathways were identified by proteomics following reintroduction of BAP1 into BAP1-null NCI-H226 lung cancer cells; however, the specific proteins and cellular responses differ, reinforcing the context-specific nature of BAP1 function." (PMID 36669126, 2023). "The overexpression of wild‐type BAP1 in lung cancer NCI‐H226 cells can significantly inhibit the tumorigenic ability of cells in nude mice." (PMID 33529461, 2021). "An immunoblotting assay (IB) was adapted to detect baseline expression of BAP1 in four lung cancer cell lines, H1299, H1650, H1299 and H1650, to determine the best lines for subsequent functional experiments." (PMID 27553041, 2016). "In contrast, there is little research paper exploring the effect of BAP1 on tumor metastasis, particularly in lung cancer." (PMID 27553041, 2016). "Because miRNAs play important roles in post-transcriptional regulation, it is quite likely that miRNAs inhibit BAP1 expression in human lung cancer." (PMID 26885612, 2016).
lung carcinoma (continued). "This disparity between BAP1 protein and mRNA expression in lung cancer tissues strongly suggests that a post-transcriptional mechanism is involved in BAP1 regulation." (PMID 26885612, 2016). "We evaluated the biological effects of miR-31 and BAP1 on the growth of lung cancer cells in a lung cancer xenograft mouse model." (PMID 26885612, 2016). "For example, lung cancer cells with overexpressed BAP1 were reported to grow poorly and formed tumors that were approximately 10-15-fold smaller than those expressing BAP1 mutants when injected into mice." (PMID 26885612, 2016). "Next, we analyzed the biological consequences of the miR-31-driven repression of BAP1 expression in lung cancer cells." (PMID 26885612, 2016). "In this study, we identified a novel regulatory network by employing miR-31 and BAP1 to fine-tune lung cancer cell proliferation and apoptosis and showed that binding BAP1 was one mechanism by which miR-31 exerted its oncogenic function." (PMID 26885612, 2016). "In functional experiments, BAP1 has been shown to suppress lung cancer tumorigenesis in athymic nude mice, promote the cell cycle and induce both apoptosis and necrosis." (PMID 27553041, 2016). "We also provided evidence that BAP1 suppressed cell proliferation and promoted cell apoptosis, suggesting that BAP1 tended to function as a tumor suppressor in lung cancer." (PMID 26885612, 2016). "The intragenic homozygous rearrangements and deletions of the nuclear deubiquitinase (BAP1) have been found in lung carcinoma cell lines." (PMID 24981056, 2014). "Therefore, we conclude that Circ_0007552 suppresses the initiation, progression, and metastasis of lung cancer cells through the miR-7974/BAP1 axis." (PMID 40918144, 2025). "Furthermore, we demonstrated that Circ_0007552 suppresses the initiation, progression, and metastasis of lung cancer cells through the miR-7974/BAP1 axis, providing novel insights into the molecular mechanisms driving lung cancer advancement." (PMID 40918144, 2025). "BAP1’s role as a tumor suppressor has been supported by an in vivo tumorigenicity study, in whch BAP1 activity and nuclear localization restricted the growth of lung cancer cell lines." (PMID 29088836, 2017). "Because miRNAs are generally thought to have expression patterns that are opposite to that of their targets, we investigated whether miR-31 expression was inversely correlated with BAP1 expression in lung cancer." (PMID 26885612, 2016). "Taken together, this study not only revealed a critical role for miR-31 as an oncogenic miRNA in lung carcinogenesis but also explored the molecular mechanisms by which miR-31 contributed to lung cancer progression and identified BAP1 as a direct target gene of miR-31." (PMID 26885612, 2016). "Taken together, this study highlights an important role for miR-31 in the suppression of BAP1 in lung cancer cells and may provide insights into the molecular mechanisms of lung carcinogenesis." (PMID 26885612, 2016). "Moreover, we showed that miR-31 promoted proliferation and suppressed apoptosis in lung cancer cells and accelerated the development of tumor growth in xenograft mice by inhibiting BAP1." (PMID 26885612, 2016). "Thus, the 1.5-2 fold increases of miR-31 levels in lung cancer tissues are sufficient to reduce the expression of BAP1 protein in vivo." (PMID 26885612, 2016). "In this study, we showed that BAP1 was frequently decreased in lung cancer tissues." (PMID 26885612, 2016). "We first determined the expression patterns of BAP1 in human lung cancer tissues." (PMID 26885612, 2016). "Moreover, in lung cancer BAP1 is tumor‐suppressive by inhibiting the KEAP1/NRF2 signaling pathway." (PMID 40600748, 2025).
lung carcinoma (continued). "Further research on miR-31 and BAP1 may reveal a new avenue for lung cancer treatment." (PMID 26885612, 2016). "Thus, BAP1 offers a particularly promising molecular target for lung cancer therapy." (PMID 26885612, 2016). "We also observed that KEAP1 deubiquitination by BAP1 stabilizes KEAP1, suppresses NRF2 target genes, and promotes oxidative stress, thereby interfering with the growth of lung cancer cells." (PMID 35052618, 2022). "In cell line models of human embryonic kidney and lung cancer, FOXK2-mediated recruitment of BAP1 to target genes has been confirmed by another study, which identified Thr493 as the phosphorylation site of BAP-1 and that this site is necessary for interaction with the FHA domain of FOXK2." (PMID 30897782, 2019). "While BAP1 has been regarded as a tumor suppressor possessing diverse molecular mechanisms, we reveal a possibility that BAP1 might serve as a redox regulator to inhibit NRF2 target genes and suppress the growth of lung cancer cells by deubiquitinating KEAP1." (PMID 35052618, 2022). "Our study indicated that absence of nuclear BAP1 stain helps differentiate MM from lung carcinomas." (PMID 27447750, 2016). "Here, we tested the hypothesis that BAP1 immunostain might help improve the accuracy of the differential diagnosis between MM, which often shows no BAP1 nuclear staining, and lung cancer, which we predicted to be BAP1 positive." (PMID 27447750, 2016).
pleural mesothelioma (33 papers, 2014 to 2026). A neoplasm that arises from the mesothelial cells of the pleura. "BRCA1-associated protein 1 (BAP1) is frequently inactivated in pleural mesothelioma and functions as a tumor suppressor through its deubiquitinating activity." (PMID 42069682, 2026). "A bidirectional association was observed between pleural mesothelioma and kidney cancer, implicating potential genetic mechanisms such as BAP1 mutations." (PMID 41409117, 2025). "BAP1 is a crucial tumor suppressor gene frequently mutated or inactivated in pleural mesothelioma (PM) and plays a pivotal role in regulating various cellular processes, including DNA damage repair, cell cycle regulation, and chromatin remodeling." (PMID 40016284, 2025). "There have been several advances in the field of pleural mesothelioma diagnosis, with BAP1 loss and p16 fluorescence in situ hybridisation increasing the sensitivity and specificity of biopsies and pleural fluid." (PMID 38097208, 2024). "The BRCA1-associated protein 1 (BAP1) gene is of great interest because somatic (BAP1) mutations are the most common alteration associated with pleural mesothelioma (PM)." (PMID 39669009, 2024). "The authors also reported that among carriers of BAP1 null mutations, peritoneal mesothelioma was more prevalent than pleural mesothelioma, in contrast to what was observed in the general population." (PMID 35885614, 2022). "Peritoneal and pleural mesotheliomas have both been associated with sporadic and germline BAP1 mutations." (PMID 30001711, 2018). "In pleural mesothelioma, BAP1, CDKN2A, and NF are the most often mutated genes." (PMID 39407894, 2024). "In particular, germline variants of BAP1 may lead to the development of many tumor lesions, mainly uveal melanoma and pleural mesothelioma." (PMID 37909022, 2023). "Further studies could consider more survival predictors such as immunohistochemistry biomarkers (e.g., p16 or BAP1 in pleural mesothelioma), risk profiles (i.e., a combination of risk factors, which predicts survival), or more specific treatments (e.g., PD-1 PD-L1)." (PMID 30336582, 2018). "Specifically, we confirmed that the profiles corresponded to expected pleural mesothelioma-specific alterations, including changes in the BAP1 and MTAP/CDKN2A gene regions." (PMID 39920655, 2025). "We previously demonstrated that in BAP1-proficient pleural mesothelioma cells, CDKN2A is critical for mediating the response to selective EZH2 inhibition and highlighted a complex interplay between epigenetic regulation and the tumor immune microenvironment." (PMID 41226368, 2025). "Cytological diagnosis of pleural mesothelioma (PM) is controversial, even using ancillary markers (BAP1, MTAP and CDKN2A)." (PMID 38067238, 2023). "Germline mutations leading to the inactivation of BAP1 (BRCA-associated protein) were associated with familiar pleural mesothelioma almost 15 years ago and subsequent studies revealed a high incidence of BAP1 inactivation even in sporadic pleural mesothelioma." (PMID 38136262, 2023). "Of note, the father of a BAP1 heterozygous patient in our study had died from pleural mesothelioma, a tumor type that is very rare in the general population but relatively frequent in families with BAP1-TPDS." (PMID 35920959, 2023). "In this cohort, BAP1 was one of the most frequently altered genes and was found in 45.0% of pleural mesothelioma and 47.9% of peritoneal mesothelioma." (PMID 36138075, 2022). "Moreover, one parent of this patient had died of pleural mesothelioma, a rare cancer that is frequent in patients with a BAP1-TPDS." (PMID 35920959, 2023). "Copy number loss of BAP1, CDKN2A/B, LAST1/2, and NF2 is frequently found in pleural mesothelioma." (PMID 32545767, 2020). "The five most frequently altered genes in pleural mesothelioma were CDKN2A (48.2%), BAP1 (45.0%), CDKN2B (42.2%), NF2 (32.8%) and MTAP (32.3%), in peritoneal mesothelioma BAP1 (47.9%), NF2 (26.5%), CDKN2A (25.9%), CDKN2B (19.5%), PBRM1 (15.8%)." (PMID 36138075, 2022).
pleural mesothelioma (continued). "In pleural mesothelioma, Group 1 had alterations in CDKN2A/B and BAP1, Group 2 in CDKN2A/B only, Group 3 in BAP1 only and Group 4 in neither BAP1 nor CDKN2A/B." (PMID 36138075, 2022). "The immunohistochemical MTVT profile is similar to that of pleural mesothelioma, including the expression of calretinin, WT1, and D2-40; MTAP and BAP-1 expression may be lost." (PMID 39682143, 2024).
peritoneal mesothelioma (29 papers, 2016 to 2026). A benign or malignant mesothelial neoplasm that arises from the peritoneum. "In a genomic analysis including 19 peritoneal mesothelioma, BAP1 loss was associated with lower PD-L1 expression." (PMID 40361508, 2025). "In malignancies like peritoneal mesothelioma, BAP1 inactivation was linked to increased tumor infiltrated immune cells and cell-attracting chemokines." (PMID 39350280, 2024). "Olaparib efficacy was quite limited in refractory pleural and peritoneal mesothelioma patients, including patients with mutation in DNA repair genes (BAP1, MRE11A)." (PMID 37686585, 2023). "The trial enrolled a total of twenty-three patients (sixteen with pleural and seven with peritoneal mesothelioma), out of which eleven had a BAP1 mutation (eight somatic and four germline), and one had both somatic BAP1 and germline MRE11A mutations." (PMID 37298116, 2023). "Leblay (2016) observed that loss of BAP1 nuclear expression and its complete tumor suppressor activity occurred in 57% of their peritoneal mesothelioma cases." (PMID 36765620, 2023). "Loss of BAP1 has been described as a candidate predictive marker of immunotherapy response in MPM and in peritoneal mesothelioma BAP1 loss has been linked to an inflammatory tumour microenvironment with increased T cell infiltrate." (PMID 35637530, 2022). "Loss of expression of BAP1 (BRCA-associated protein 1) has been shown to have high specificity for differentiating peritoneal mesothelioma from benign mesothelial proliferation." (PMID 34817720, 2021). "Early recognition of signs and symptoms of peritoneal mesothelioma in patients who carry germline BAP1 mutations can impact outcome and survival." (PMID 30001711, 2018). "Furthermore, in the peritoneal mesothelioma cohort in the previously cited study, the most common alterations detected in peritoneal mesothelioma were inactivating mutations in BAP1 (47.9%), NF2 (26.5%), CDKN2A (25.9%), CDKN2B (19.5%) and PBRM1 (15.8%)." (PMID 38136262, 2023). "Interestingly, there was a greater frequency of peritoneal mesothelioma cases in those with the BAP-1 mutation and asbestos exposure." (PMID 36653798, 2023). "Recent investigations in peritoneal mesothelioma have suggested that BAP1 haploinsufficiency is correlated with an inflammatory tumor microenvironment and may be a potential prognostic and predictive biomarker for immunotherapy." (PMID 32944962, 2021). "Studies in peritoneal mesothelioma and RCC patients have shown BAP1-related tumors have an inflammatory microenvironment, with increased immune cell tumor infiltration and PD-L1 expression." (PMID 35381901, 2022). "The study included 23 patients with pleural or peritoneal mesothelioma, irrespective of BAP1 or BRCA1 status." (PMID 40361508, 2025). "For patients with peritoneal mesothelioma, no asbestos exposure, younger age, and previous tumors history, BAP1 gene testing is recommended." (PMID 37461124, 2023). "BAP1 is only occasionally altered (0.3%) in serous ovary carcinoma, which further supports its utility in supporting a pathological diagnosis of peritoneal mesothelioma rather than gynecological carcinoma." (PMID 34294087, 2021). "Third, given the similar genomic landscape of both pleural and peritoneal mesothelioma (copy number-driven somatic alterations including high BAP1 and CDKN2A inactivation frequency), there was no expectation of widely differing responses to anti-PD-1 checkpoint inhibition between these subtypes." (PMID 34656227, 2021).